RN7SL291P (RNA, 7SL, cytoplasmic 291, pseudogene)
Gene: Miscellaneous RNA gene on chromosome X (44,772,773 to 44,773,061, reverse strand). Ensembl gene ENSG00000242065.
Homologues: Orthologues: chimpanzee Metazoa_SRP (99% identical), macaque Metazoa_SRP (97% identical). Paralogues in human: RN7SL1 (82% identical), RN7SL2 (82% identical), RN7SL220P (82% identical), RN7SL3 (82% identical), RN7SL448P (80% identical), RN7SL493P (80% identical), RN7SL126P (79% identical), RN7SL18P (79% identical), RN7SL301P (79% identical), RN7SL444P (79% identical), RN7SL709P (79% identical), RN7SL597P (79% identical), and 702 more.